MALAT1 (metastasis associated lung adenocarcinoma transcript 1)
Diseases named in the same sentence as MALAT1 in open-access papers (continued):
Sharing a sentence is not in itself a finding about the gene and the disease.
breast cancer (continued). "To determine the molecular mechanism behind MALAT1 regulation, we examined if FOXO1 can bind to the MALAT1 promoter in breast cancer cells." (PMID 32708561, 2020). "Besides, MALAT1 was one of the top 10 up-regulated DElncRNAs in this study, and co-expressed with S100A7, which emphasized the critical role the MALAT1 in luminal B breast cancer and suggested that MALAT1 may involve in luminal B breast cancer by regulating S100A7." (PMID 31795964, 2019). "By regulating MALAT1, TALAM1 reveals the functional properties of natural antisense transcripts in gene regulation and cancer networks, raising new candidates for breast cancer targeting." (PMID 31382922, 2019). "Recently, MALAT1 was also considered a proinflammatory factor which regulated the lipopolysaccharide (LPS)-induced inflammatory response and EMT process of breast cancer cells." (PMID 31214490, 2019). "In conclusion, MALAT1 acts as ceRNA of Cdc42 by binding to miR-1 and then leads to EMT in human breast cancer cell lines." (PMID 31214490, 2019). "Among these genes, two were non-coding, MALAT1 and NEAT1, of which both are connected to CSC properties in several cancer types, including breast cancer." (PMID 31191614, 2019). "The expression of MALAT1 in clinical samples with TNBC and Her-2 positive breast cancers was tested by qRT-PCR." (PMID 29416769, 2018). "From the perspective of the mechanisms, our findings demonstrated that XBP1 and HIF-1α are upstream driver genes of MALAT1 in TNBC cells, while Her-2 is an upstream driver gene of MALAT1 in Her-2 positive breast cancer cells." (PMID 29416769, 2018). "Using chromatin isolation by RNA purification coupled to mass spectrometry (ChIRP-MS) studies, they demonstrated that Malat1 sequestered the transcription factor TEAD, thus inhibiting its activity in mouse mammary tumors." (PMID 30545127, 2018). "On the contrary, a recent study showed that MALAT1 is downregulated in CRC and various subtypes of breast cancer." (PMID 29702599, 2018). "In a mouse MMTV (mouse mammary tumor virus)-PyMT breast cancer model, enhanced cell adhesion and cystic differentiation and reduced migration were shown upon ASO-targeted knockdown of MALAT1." (PMID 30466456, 2018). "In the recent decade, numerous studies have revealed the potential of MALAT1 in modulating the invasion, migration and metastasis of various cancers, including ESCC, breast cancer, CRC and osteosarcoma." (PMID 29368602, 2018). "For example, KCNQ1OT1, MALAT1, XIST, and NEAT1 are experimentally confirmed breast cancer-related lncRNAs, which have been ranked 2nd, 11th, 12th, and 19th in the predicted list based on the model of DCSLDA, respectively." (PMID 30046354, 2018). "By crossbreeding MALAT1 KO female mice with male mice with high incidence of mammary tumor (MMTV-PyMT mice), three filial generations were obtained (MMTV-PyMT Malat1+/+; MMTV-PyMT Malat1+/−; MMTV-PyMT Malat1−/− mice)." (PMID 27732939, 2017). "AHIF, MALAT1, SNHG6, UCA1 expression levels increased in breast cancer tissues compared with their counterpart adjacent tissues, while AFAP1-AS1, PVT1, HYMAI had lower expression in tumors." (PMID 28938549, 2017). "The results also showed that MALAT1-siRNA repressed breast cancer cell proliferation, whereas CDK4 overexpression induced breast cancer cell proliferation." (PMID 26918449, 2016). "Furthermore we wanted to know whether MALAT1 increased CDK4 expression in breast cancer." (PMID 26918449, 2016). "We validated that the treatment with MALAT1-siRNA and CDK4 attenuated the effect of MALAT1 on breast cancer cells proliferation." (PMID 26918449, 2016). "In both PCa and breast cancer cells 45 min of estrogen treatment was sufficient to induce a consistent increase of eNOS recruitment onto the HOTAIR and MALAT1 promoter regions as compared to basal condition." (PMID 27922078, 2016).
breast cancer (continued). "We identified a strong positive link between Δsv-MALAT1 overexpression and DGCR8 expression, suggesting that Drosha-DGCR8 complex (Microprocessor) controlled the abundance of Δsv-MALAT1 in breast cancer as in HEK 293T cells." (PMID 27172249, 2016). "In the current study, by examining MALAT1 expression on mRNA level, we demonstrated that compared with MCF10A, MALAT1 expression was up-regulated in the majority of breast cancer cell lines (9/12)." (PMID 27191888, 2016). "MALAT1 was highly expressed in several cancer types, such as NSCLC, gastric cancer, colorectal cancer, breast cancer, cervical cancer, prostate cancer, nasopharyngeal cancer, and renal cancer." (PMID 27527868, 2016). "Taken together, miR-124 is suppressed by MALAT1, and involved in cell proliferation and the cell cycle via the CDK4/E2F1 signaling pathway in breast cancer." (PMID 26918449, 2016). "It should be also noted that our ERα-dependent lncRNA set does not contain most of the lncRNAs that were previously studied in breast cancer, such as HOTAIR, CCAT2, UCA1, MALAT1, BCAR4, EGOT, SPRY4-IT1 and others." (PMID 26621851, 2016). "Therefore, this study aims to investigate the expression patterns and potential regulatory relationships between key transcription factors (FOXC2, SNAIL, and ZEB) and oncogenic lncRNAs (HOTAIR, MALAT1, and UCA1) in metastatic breast cancer stem cells." (PMID 40781106, 2025). "In HER2-positive breast cancer, elevated expression of PAK5 promotes m6A modification of lncRNA MALAT1 through phosphorylation of the methyltransferase METTL14 at serine 399, thereby stabilizing MALAT1 RNA level." (PMID 40258843, 2025). "A number of promising lncRNAs show altered expression in many tumor types, e.g., PCA3 (in prostate cancer), HOTAIR (breast cancer, laryngeal squamous cell carcinoma, cervical cancer, and urothelial bladder cancer), BCAR4 (colorectal cancer), and MALAT1 (non-small cell lung cancer)." (PMID 40002172, 2025). "HCT116 cells were treated with 1 μM of each TBM because previously 1 μM of compound 5 and 1 μM of quercetin were shown to decrease MALAT1 levels by ~50% in the mouse mammary tumor virus-polyoma middle tumor-antigen (MMTV-PyMT) tumor organoid model and MCF7 breast cancer cell lines, respectively." (PMID 41226238, 2025). "In HER2-positive breast cancer, elevated expression of PAK5 promotes m6A modification of lncRNA MALAT1 through phosphorylation of the methyltransferase METTL14, thereby stabilizing MALAT1 RNA level." (PMID 40258843, 2025). "Earlier findings showed that in non-metastatic MCF7 cells (a cell model of luminal ER+ breast cancer), HuR, and MALAT1 form repressive chromatin complexes that impact CD133 expression, suppressing EMT." (PMID 38254873, 2024). "The results showed that the NR4A1 gene was specifically regulated by MALAT1 in MCF7 breast cancer cells but not in pancreatic ductal adenocarcinoma PANC1 cells." (PMID 38791553, 2024). "For example, the roles of integrin and human epidermal growth factor receptor, FZD6 and Malat1 long non-coding RNAs in pretumor tissues have been confirmed, revealing the importance of RANK ligand and JNK in the development of breast cancer and breast cancer." (PMID 38342791, 2024). "Furthermore, inferior overall survival and disease-free survival of patients exhibiting high MALAT1 expression have been reported in numerous types of cancer, such as ESCC, gastric cancer, prostate and breast cancer." (PMID 38203269, 2023). "In breast cancer cells, METTL3 mediates methylation of the lncRNA MALAT1 that promotes metastasis." (PMID 37369946, 2023). "The results seemed to suggest that MALAT1 couldbe a potential biomarker and a therapeutic target in HER2+ breast cancer." (PMID 37538803, 2023). "Similarly, the metformin-regulated expression of MALAT1, HOTAIR, and TUG1 was reported to be upregulated in breast cancer cells." (PMID 38053839, 2023).
breast cancer (continued). "Moreover, miR-1 has been shown to suppress breast cancer development by downregulating KRAS and MALAT1 transcription, which emphasizes the potential role of miR-1 as a tumor-suppressive miRNA and MALAT1 as an oncogenic lncRNA via the regulation of KRAS." (PMID 34489556, 2022). "Recently, the presence of lncRNA MALAT1 has also been detected in exosomes from various cancer cell lines, included TNBC cells, and it was shown that exosomal MALAT1 exerts an autocrine pro-proliferative role on MDA-MB-231 breast cancer cells." (PMID 35076579, 2022). "Reduced expression of BLACAT1 in HNSCC; MALAT1, NEAT1 and PVT1 in NPC; FAM201A, PVT1 and LINC00857 in NSCLC; LINC00473, CCAT2and Rpph1 in EC; HOTAIR and LINC00958 in CRC; AFAP1-AS1 and LINC00511 in breast cancer were correlated with radiosensitivity." (PMID 36323697, 2022). "One of the few studies that performed DNAse treatment before quantification of MALAT1 expression demonstrated that MALAT1 is a metastasis-suppressing lncRNA rather than a metastasis promoter lncRNA in breast cancer." (PMID 34202021, 2021). "Our findings provide evidence that hypoxia-responsive long non-coding MALAT1 could be transcriptionally activated by HIF-1α and HIF-2α, act as a miRNA sponge of miR-3064-5p, and promote tumor growth and migration in breast cancer cells." (PMID 34012919, 2021). "Similarly, MALAT1 and DSCAM–AS1 are found to over-expressed in breast cancer patients with poor outcomes, unfortunately, we cannot observe this information from our results." (PMID 34082714, 2021). "For example, it was reported that lncRNA MALAT1 could bind to and inactivate the pro-metastatic transcription factor TEAD to suppress breast cancer metastasis." (PMID 34601496, 2021). "The altered lncRNAs in tumors are expected to be used as diagnostic markers in multiple tumors, such as lncRNA HOTAIR (in breast cancer) and lncRNA MALAT1 in liver cancer, breast cancer, non-lung small cell carcinoma, colon cancer and prostate cancer." (PMID 34399848, 2021). "Ligand-receptor interactions and potential regulatory mechanisms were explored and the LINC00276&MALAT1/miR-206/FZD4-Wnt7b pathway was identified to play an important role in the functions of these genes and can be used to explore targets against breast cancer metastasis and recurrence." (PMID 34457116, 2021). "As MALAT1 and NEAT1 are consistently upregulated under hypoxia in these breast cancer cell lines, we asked if hypoxia could upregulate eNEMAL as well." (PMID 34019552, 2021). "MALAT1 binds to the transcription factor TEAD and inactivates the transcriptional activity of the YAP/TEAD complex, subsequently inhibiting the metastatic ability of breast cancer cells." (PMID 34446703, 2021). "Taken together, these data suggested that hypoxia-responsive long non-coding MALAT1 could be transcriptionally activated by HIF-1α and HIF-2α, act as a miRNA sponge of miR-3064-5p, and promote tumor growth and migration in breast cancer cells." (PMID 34012919, 2021). "Assessment of expression of VDR and these lncRNAs in breast cancer tissues and adjacent non-cancerous tissues (ANCTs) has led to identification of aberrant expression of MALAT1 and LINC00511 in tumoral specimens." (PMID 32514489, 2020). "Conversely, MALAT1 binds to an RNA-binding protein, Hu antigen R (HuR), and interacts with the CD133 gene to downregulate CD133, thus suppressing the epithelial-to-mesenchymal transition (EMT) and migration activity of breast cancer cells." (PMID 32486413, 2020). "The downregulation of MALAT1 enhanced trastuzumab-inhibiting cell viability and reduced the number of invaded cells, suggesting a potential role for MALAT1 in decreasing sensitivity of trastuzumab in HER2+ breast cancer cells." (PMID 32708561, 2020). "MALAT1 expression was examined in 13 breast cancer tissues and seven non-cancer tissues through mRNA-seq." (PMID 32708561, 2020).
breast cancer (continued). "Nevertheless, the prognostic role of MALAT-1 in breast cancer is poorly characterized, with no systematic evaluation conducted to date." (PMID 32700729, 2020). "The lncRNA MALAT1 was shown to contribute to tumor progression in ER‐positive (also known as luminal) cell lines and has been shown to control the expression of CD133 in the dedifferentiation process of breast cancer cells." (PMID 32392629, 2020). "Consistent with that, some studies previously reported that M2 macrophage secreted IL-8 via the STAT3/MALAT1 pathway to promote prostate tumorigenesis, and ERK/STAT3 axis could drive breast cancer progressions by stimulating M2 macrophage." (PMID 32486001, 2020). "The expression of MALAT1 was significantly higher in breast cancer tissues than that in non-cancer tissues." (PMID 32708561, 2020). "Our comprehensive meta-analysis of 4186 cases from 12 cohorts showed that high MALAT-1 expression levels in patients with breast cancer were observed in most studies, with no obvious subtype or cell specificity." (PMID 32700729, 2020). "For instance, MALAT1 interacts with the promoter of the eukaryotic translation elongation factor 1 alpha 1 (EEF1A1) gene and upregulates EEF1A1 expression by enhancing the trimethylation of H3K4, which promotes the proliferation and invasion of breast cancer." (PMID 32486413, 2020). "Compared to non-breast cancer cells MCF12A, expression of MALAT1 was significantly upregulated in all subtypes of breast cancer cells." (PMID 32708561, 2020). "Interestingly, simultaneous knockdown of both MALAT1 and TALAM1 in breast cancer cells led to a stronger, synergistic decrease in migration and invasion of these cells and reduced metastasis to the lungs in a mouse model." (PMID 32503170, 2020). "The PI3K/Akt pathway mediating FOXO1 binding to the promoter of MALAT1 could be a mechanism for MALAT1 inducing EMT and reducing trastuzumab sensitivity in HER2+ breast cancer." (PMID 32708561, 2020). "Among the candidates unique to our study are several proteins described to be involved in different cancer types in humans: for example, NOLC1 in multidrug resistant non-small cell lung cancer (the same cancer MALAT1 has originally been identified), DEK in breast cancer and SUB1 in prostate cancer." (PMID 32050583, 2020). "The subgroup analysis for cancer type suggested that MALAT-1 up-regulation was a strong prognostic biomarker in both patients with TNBC (HR = 1.88, 95% CI = 1.45‒2.44, P<0.0001) and in those with mixed type breast cancer (HR = 2.57, 95% CI = 1.71‒3.85, P<0.0001)." (PMID 32700729, 2020). "Here using a collection of breast cancer cells and in vitro and in vivo migration assays we characterized the dynamics of expression and demonstrated that TALAM1 regulates and synergizes with MALAT1 during tumorigenesis." (PMID 31382922, 2019). "One study found that the level of MALAT1 expression was positively correlated with lymph node metastasis in breast cancer patients and had a significant negative correlation with 5-year disease-free survival (DFS)." (PMID 30683807, 2019). "By regulating the functional levels of MALAT1, down-regulation of TALAM1 leads to a synergistic biological effect characterized by a stronger decrease of the migration, invasion and expression properties of human breast cancer cells." (PMID 31382922, 2019). "For instance, subcutaneous injection of MALAT1-targeting ASOs in a mouse model of metastatic luminal B breast cancer resulted in the formation of cystic and non-metastatic tumors." (PMID 31003545, 2019). "To explore whether MALAT1 was involved in regulating proliferation and invasion abilities of Her-2 positive breast cancer cells via Her-2, we firstly detected the expressions of Her-2 in MDA-MD-435 by qRT-PCR after the knockdown of MALAT1." (PMID 29416769, 2018).
breast cancer (continued). "This is consistent with ceRNA studies on MALAT1 that demonstrated its regulation of various miRNA/oncogene axes to induce migration, invasion and cell proliferation in colorectal carcinoma (CRC), breast cancer, gallbladder cancer, NSCLC and oral squamous cell carcinoma (OSCC)." (PMID 29702599, 2018). "MALAT1 is known to activate WNT–β-catenin signaling, and is oncogenic in breast cancer." (PMID 30545127, 2018). "However, contradictory results have been obtained for the effect of MALAT-1 on EMT in breast cancer cells, with two studies reporting the promotion of EMT by MALAT-1 and another reporting inhibition of EMT by MALAT-1." (PMID 28430163, 2017). "It is unlikely that gene amplification is one of the mechanisms for MALAT1 overexpression because MALAT1 is located in a chromosomal region (11q13.1) non-recurrently amplified in breast cancer." (PMID 27172249, 2016). "Previous studies have demonstrated that MALAT1 expression is increased in multiple cancers, and our results supported these findings as it was significantly increased in breast cancer tissues compared with the adjacent non-tumor tissues." (PMID 26918449, 2016). "In this study, we demonstrate that regulation of aggressive breast cancer cell traits by MALAT1 is not predicted solely based on an elevated expression level but is context specific." (PMID 27250026, 2016). "As Hsa-miR-125b suppresses bladder cancer development by downregulating MALAT1, we tested the possible negative correlation between Δsv-MALAT1 and Hsa-miR-125b mRNA level in breast cancer." (PMID 27172249, 2016). "However, many recent studies have examined the roles of various lncRNAs in cancer; examples include MALAT1 in small cell lung carcinoma, lncRNA-ATB in hepatocellular carcinoma, and NKILA in breast cancer." (PMID 27223436, 2016). "In addition, we validated that the treatment with MALAT1 and CDK4-siRNA attenuated the effect of MALAT1 on breast cancer cells proliferation." (PMID 26918449, 2016). "RNA-ChIP with MALAT1 revealed a differential response: interaction between MALAT1 and ERβ in PCa cells and or between MALAT1 and ERα in breast cancer cells, both detectable in basal condition, was not affected by E2 treatment." (PMID 27922078, 2016). "The expression of MALAT1 tended to be higher in breast cancer tissues than in normal tissue but was not significantly different between the two (P = 0.075)." (PMID 27191888, 2016). "Then, we detected the expression of MALAT1 in 33 pairs of breast cancer tissues and their adjacent normal tissues." (PMID 27191888, 2016). "A very recent study reported that in luminal B breast cancer model system, depletion of MALAT1 did not alter the expression of genes involved in EMT, even though the cells showed defects in tumor progression and metastasis." (PMID 27250026, 2016). "For example, lncRNAs such as HOTAIR (breast cancer), NKILA (breast cancer metastasis), NBAT1 (neuroblastoma), MALAT1 (lung, breast, prostate and cervix cancer), MDC1-AS (bladder cancer), lncRNA-886 (esophageal and gastric cancers) and PCAT-1 (prostate cancer) have been implicated in tumorigenesis." (PMID 26087192, 2015). "Moreover, MALAT1 inhibits ubiquitin-proteasomal degradation of the N-HER2 by affecting the binding of deubiquitinase USP8 and N-HER2, thereby promoting N-HER2 accumulation and trastuzumab resistance in HER2-positive breast cancer." (PMID 40258843, 2025). "For example, hypoxia-inducible factor 1α (HIF-1α) upregulates MALAT1 with the mediation of AMP-activated protein kinase (AMPK); the induced lncRNA then acts as a miRNA sponge of miR-3064-5p, a mechanism that promotes tumor growth and migration in breast cancer cells." (PMID 40951838, 2025). "Moreover, across the four patient groups, MALAT1 expression levels in pre-osteoclasts and osteoclasts were significantly lower in patients with osteoporosis, osteosarcoma, or breast cancer bone metastasis than in the non-osteoporotic individual." (PMID 38493144, 2024).